TRPV4 (transient receptor potential cation channel subfamily V member 4)
Diseases named in the same sentence as TRPV4 in open-access papers (continued):
Sharing a sentence is not in itself a finding about the gene and the disease.
asthma (26 papers, 2008 to 2026). "Blocking TRPV4 with HC-067047 effectively mitigated asthma exacerbation caused by combined exposure." (PMID 41893487, 2026). "An increased expression of TRPV4 in bronchial epithelial cells has been linked to a higher risk of sensitization to fungal allergens and asthma." (PMID 38543079, 2024). "Increased HBEC expression of TRPV4 is associated with increased risk of fungal allergen and asthma sensitization in a mouse model of asthma." (PMID 38033335, 2023). "In a translational approach, the authors also reported that a single nucleotide polymorphism (SNP) rs6606743 in the human Trpv4 gene increased the expression of the channel protein and is associated with fungal immunization and asthma in humans." (PMID 36139480, 2022). "TRPV4 has been implicated in the pathogenesis of asthma, CF, and sterile and infection-associated ARDS." (PMID 28523001, 2017). "TRPV4’s overactivity and/or dysfunction has been associated with several diseases, such as skeletal dysplasias, neuromuscular disorders, and lung pathologies such as asthma and cardiogenic lung edema and COVID-19–related respiratory malfunction." (PMID 36549871, 2023). "The specific single nucleotide polymorphism, rs6606743 of TRPV4, was found to significantly contribute to the development of osmotic airway hyperresponsiveness in patients with asthma showing uncontrolled bronchial asthma compared to control patients having negative response to bronchoprovocation." (PMID 38033335, 2023). "Moreover, a single nucleotide polymorphism (SNP) rs6606743 in the human TRPV4 gene increased expression of the channel protein and is associated with fungal immunization and asthma in humans." (PMID 33917551, 2021). "Our data highlight novel essential functions of TRPV4 channels in secretion of SP-A and SP-D, which are important not only for innate immunity, but also for lung diseases like asthma and Idiopathic Pulmonary Fibrosis (IPF)." (PMID 41738221, 2026). "The interaction between TRPV4 and NOX4 can be targeted to mitigate lung remodelling associated with asthma." (PMID 38365763, 2024). "Studies in mice models have demonstrated that TRPV4 influences airway wall thickness, collagen synthesis, goblet cell recruitment, and fibrosis, which are key features of asthma pathology." (PMID 39664985, 2024). "More important, it has been found that TRPV4, TRPM8, and TRPC1 are primarily associated with obese asthma through their role in inflammation, and they are also linked to the production of fat and inflammatory factors." (PMID 39664985, 2024). "We will discuss the role of TRPV4 in the inflammatory process, especially in macrophages, to demonstrate the importance of TRPV4 in the inflammatory process of obese asthma and the feasibility of targeting TRPV4 in the treatment of obese asthma." (PMID 38365763, 2024). "Nevertheless, the overall consensus supports the universal role and significance of TRPV4 in inflammatory diseases, including asthma." (PMID 38365763, 2024). "TRPV4 is expressed in goblet cells and ciliated cells within the respiratory tract and plays a crucial role in airway inflammation, including asthma." (PMID 38365763, 2024). "We hope that future research can focus on exploring effective activators or inhibitors of TRPV4, which are harmless to the human body and can be modified as new targeted drugs for treating obese asthma." (PMID 38365763, 2024). "Among TRP channels, TRPA1, TRPV1, and TRPV4 are relevant to asthma due to their widespread expression in the respiratory system." (PMID 39664985, 2024). "Here, it is shown that TRPV4 is inhibited by bronchodilators widely used in diseases such as asthma." (PMID 36549871, 2023). "In a mite-induced asthma model, knockout mice for this channel (TRPV4−/−) was protected from airway remodeling." (PMID 37841931, 2023). "There are several lines of evidence for the important role of TRPV4 channels in asthma and inflammation of the airways." (PMID 36139480, 2022).
asthma (continued). "In most of the cells, TRP channels are expressed, and strong evidence for an essential role in airway function and associated diseases, such as CF, asthma, fibrosis and edema was demonstrated for TRPA1, TRPC6, TRPM2, TRPM5, TRPM7, TRPV2, TRPV4 and TRPV6." (PMID 36139480, 2022). "Another research group showed in a mouse model for asthma that, among others, TRPV4 protein levels are increased after nanoTiO2 inhalation." (PMID 36139480, 2022). "The transient receptor potential vanilloid 4 (TRPV4) channel is involved in a series of diseases such as asthma, cancer, anxiety, and cardiac hypertrophy." (PMID 35431940, 2022). "Accumulating evidence indicates that TRPV4 is involved in a variety of lung diseases, including cough, asthma, COPD, idiopathic pulmonary fibrosis, and acute respiratory distress syndrome." (PMID 35002766, 2021). "In a chicken ovalbumin (OVA) model of asthma, TRPV4-/- mice developed similar levels of airway hyper-responsiveness compared to wild-type (WT) mice, although TRPV4 protein levels were increased in WT animals." (PMID 33917551, 2021). "Bronchospasm and asthma-like symptoms developed in response to the action of cold air and high humidity are associated with the participation of TRPV1, TRPV4, and TRPV2 channels in osmoreception." (PMID 34356881, 2021). "Accumulating evidence indicates that TRPV4 is involved in a variety of lung diseases, including cough, asthma, COPD, idiopathic pulmonary fibrosis (IPF), and acute respiratory distress syndrome." (PMID 35002766, 2021). "In separate studies, Paruchuri and colleagues demonstrated that TRPV4 mediates airway remodeling and fibrosis in a mouse model of allergen-induced asthma." (PMID 34831281, 2021). "Employing a model of Dermatophagoides farinae (D.farinae)-induced asthma, we recently reported that TRPV4 KO mice were protected from D.farinae -induced airway remodeling." (PMID 32555397, 2020). "In asthma, TRPV4 mediates hypotonicity-induced airway hyperresponsiveness, but not release of Th2 cytokines." (PMID 28523001, 2017). "TRPV4 indirectly mediates hypotonicity-induced smooth muscle contraction and airway remodeling in asthma." (PMID 28523001, 2017). "Targeting TRPV4 may offer a potential therapeutic strategy to mitigate asthma exacerbation in environments with high humidity and PM2.5." (PMID 41893487, 2026). "Due to the high expression of certain TRP channels, particularly in immune cells like macrophages, and the findings from previous research, as well as their clear or potential involvement in the inflammatory process of obese asthma, we have specifically chosen to discuss TRPV4, TRPM8, and TRPC1." (PMID 38365763, 2024). "Overall, TRP channels, including TRPA1, TRPV1, and TRPV4, contribute to asthma pathophysiology and the immune response by regulating inflammatory processes, immune cell recruitment, and airway remodeling, making them potential therapeutic targets for asthma management." (PMID 39664985, 2024). "TRPV4 knockout could protect from airway remodeling in asthmatic mice model, emphasizing its role in asthma-related structural changes." (PMID 39664985, 2024). "The TRPV4 gene SNP rs6606743 located in the 5′-upstream region has been revealed to make a significant contribution to the development of osmotic airway hyperresponsiveness in patients with uncontrolled asthma." (PMID 34356881, 2021). "Moreover, TRPV4 is an excellent therapeutic target with numerous specific compounds regulating its activity in diseases, like asthma, lung fibrosis, edema, and infections." (PMID 33917551, 2021). "Importantly, fibroblasts isolated from patients with asthma exhibited enhanced TRPV4 expression and increased fibrotic gene expression (α-SMA) in response to TGF-β1 compared to normal fibroblasts." (PMID 34831281, 2021). "Another SNP of TRPV4—a missense variation rs3742030 (p.Pro19Ser)—demonstrated a lack of association with childhood asthma and cough or current wheezing as markers of active disease." (PMID 34356881, 2021).
asthma (continued). "In conclusion, our results suggest that targeting TRPV4/NOX4 signaling may provide a new therapy for lung remodeling in asthma in situations where treatments focused solely on steroids or other conventional treatments have proven ineffective." (PMID 32555397, 2020). "Therefore, TRPA1, TRPV1, and TRPV4 are most promising pharmacological targets for new asthma therapeutics and already effective modulators are ready for use in clinical trials." (PMID 30717260, 2019). "In the present review, we discuss the role of the mechanosensitive cation channel, transient receptor potential vanilloid 4 (TRPV4), in cytokine secretion and pulmonary inflammatory diseases such as asthma, cystic fibrosis, and acute lung injury/acute respiratory distress syndrome (ARDS)." (PMID 28523001, 2017). "Whether this TRPV4-mediated neural and immune interaction indeed plays a role in the pathogenesis of asthma remains to be investigated." (PMID 26973533, 2016). "TRPV4 knockout studies have however revealed a physiological role and predicted involvement of TRPV4 in diseases like thermal hyperalgesia, neuropathic pain, hyperresponsive airway during asthma, hypotonic stress during cystic fibrosis, impairment of hearing." (PMID 19305786, 2008). "Perhaps activating the TRPV4 channel on adipocytes or immune cells can reduce the secretion of leptin and adiponectin, prevent the content of adipocytokines in the surrounding blood, inhibit the occurrence of airway hyperresponsiveness, and ultimately achieve the goal of controlling asthma." (PMID 38365763, 2024). "In addition, TRPV4 has been implicated in the inflammatory response of the airways and the proliferation of ASM cells, which may contribute to the pathogenesis of asthma and COPD." (PMID 38543079, 2024). "Considering the multiple roles of TRPV4 in the respiratory tract function, targeting TRPV4 could be an effective approach to treat respiratory diseases like asthma or COPD, which involve mechanical stress on several entities such as ASM cells, epithelial, and inflammatory cells in the airways." (PMID 38543079, 2024). "Therefore, based on these studies, it is suggested that reduced activation of TRP family channels, especially TRPA1, TRPV1 and TRPV4, may be potential targets for new therapies for asthma." (PMID 37841931, 2023). "Importantly, diesel exhaust particles (DEP) evoked protracted Ca2+ influx via TRPV4, enhanced by the COPD-predisposing human genetic polymorphism TRPV4P19S Therefore, TRPV4 antagonists may present options for cough relief, asthma, and COPD therapeutics." (PMID 33917551, 2021). "However, the mechanism through which TRPV4 is activated or whether and how TRPV4 facilitates fibroblast differentiation and matrix remodeling, specifically in asthma, is still elusive." (PMID 32555397, 2020). "This review will focus on TRP channels (TRPA1, TRPC6, TRPV1, and TRPV4), predominantly expressed in non-neuronal lung tissues and their involvement in pathways associated with diseases like asthma, cystic fibrosis, chronic obstructive pulmonary disease (COPD), lung fibrosis, and edema formation." (PMID 30717260, 2019). "Furthermore, high humidity conditions may potentiate the activation of pulmonary transient receptor potential vanilloid 4 (TRPV4) ion channels, resulting in heightened airway inflammation and excessive mucus secretion, which can contribute to the pathogenesis of asthma." (PMID 39713043, 2024). "Our findings suggest that TRPV4 integrates TGFβ1 and ROS signaling through NOX4 and, TRPV4-NOX4 interaction is amenable to target lung remodeling during asthma." (PMID 32555397, 2020). "In this study, we demonstrated that mechanosensitive ion channel TRPV4 integrates growth factor (TGFβ1) and redox (NOX4) signaling during lung fibroblast differentiation and airway remodeling in asthma." (PMID 32555397, 2020).
asthma (continued). "Because ASM contraction is partially regulated by Ca2+ influx via NSCCs, it is believed that mechanosensitive channels such as TRPV4 may play a role in dysregulated ASM contraction and asthma." (PMID 38543079, 2024). "TRPV4 has been found to play important roles in both HASM and HBECs in the setting of asthma." (PMID 38033335, 2023). "Therefore, the development of bronchospasm and asthma-like symptoms in response to the action of hyper- and hypoosmolar exogenous stimuli is mediated by the vanilloid receptors, such as TRPV1, TRPV4, and TRPV2." (PMID 34356881, 2021). "To understand the significance of the TRPV4-NOX pathway in fibroblast differentiation in asthma, we took advantage of fibroblasts isolated from normal (NHLF) and from patient suffering from asthma exacerbation (DHLF) and analyzed NOX4 expression in both cell types." (PMID 32555397, 2020). "Several P2X receptors are expressed on human lung mast cells (HLMCs), and so we hypothesised that the TRPV4–ATP axis plays a role in human ASM–HLMC crosstalk, evoking mast cell-dependent bronchospasm which may play a key role in asthma pathophysiology." (PMID 32299856, 2020). "While asthma is an inflammatory disease, there is no current evidence linking Th2-type cytokines and TRPV4 in the pathogenesis of asthma." (PMID 28523001, 2017). "Associations between SNPs in TRPV4 and TRPA1 and cough symptoms in subjects with or without asthma were also not significant after adjusting for multiple testing." (PMID 22443337, 2012). "TRPV4 is also expressed in human airway smooth muscle cells, and specific agonists induce the release of ATP in non-atopic, immunoglobulin E-independent asthma patients." (PMID 36139480, 2022). "Recent work shows that TRPV4 mediates airway wall thickness, goblet cell recruitment, collagen expression, fibrotic airway remodeling, and increased expression of transforming growth factor-β (TGF-β) in a house dust mite (Dermatophagoides farinae) mouse model of asthma." (PMID 28523001, 2017). "TRPV4 agonists induced the release of ATP from human airway smooth muscle cells (HASMC) of non-atopic, immunoglobulin E-independent, asthma patients." (PMID 33917551, 2021).
pulmonary fibrosis (26 papers, 2016 to 2026). Chronic progressive interstitial lung disorder characterized by the replacement of the lung tissue by connective tissue, leading to progressive dyspnea, respiratory failure, or right heart failure. "We demonstrate that loss of TRPV4 specifically in myeloid cells protects against experimental pulmonary fibrosis in vivo." (PMID 41513093, 2026). "A novel finding in lung fibrosis is that TRPV4 physically associates with PI3Kγ, a class I phosphoinositide 3-kinase isoform, forming a mechanosensitive signaling module." (PMID 40149956, 2025). "Increased TRPV4 expression is associated with skin fibrosis in scleroderma, while TRPV4 channel activity is enhanced in lung fibroblasts from patients with idiopathic pulmonary fibrosis." (PMID 38612378, 2024). "TRPV4 expression was demonstrated to be upregulated in bleomycin-induced fibrosis in mice and that TRPV4-deficient mice were protected from bleomycin-induced pulmonary fibrosis via reducing fibroblast differentiation, resulting in reduced mortality rates." (PMID 34831281, 2021). "TRPV4 is constitutively expressed in primary lung fibroblasts and a global TRPV4-deficient mouse model showed less fibrotic plaques and was partly protected from bleomycin-induced lung fibrosis." (PMID 33917551, 2021). "Recently, we reported that transient receptor potential vanilloid 4 (TRPV4), a mechanosensitive Ca2+‐permeable channel, is associated with skin and lung fibrosis." (PMID 30450767, 2019). "Deficiencies of TRPC6 and TRPV4 independently protected lungs in a mouse model of bleomycin-induced lung fibrosis." (PMID 30717260, 2019). "Furthermore, TRPV4 mechanotransduction increases on stiffer matrices or in fibrotic lung tissue, while Trpv4-deficient mice are protected from bleomycin-induced lung fibrosis." (PMID 38256251, 2024). "The mechanosensitive channel, TRPV4 has been implicated in mouse models of lung injury/fibrosis, which include hydrochloric acid, pulmonary edema, ventilator-associated lung parenchymal overdistension, and from our group, pulmonary fibrosis." (PMID 32676078, 2020). "Lung fibrosis was also attenuated by the loss of TRPV4 gene function." (PMID 28030558, 2016). "Studies of TRPV4 expression and activity in fibroblasts suggest that increased TRPV4 expression is associated with skin fibrosis in scleroderma and that the activity of TRPV4 channels is increased in the lung fibroblasts of patients with idiopathic pulmonary fibrosis." (PMID 39425532, 2024). "Our findings identify AA as a potent modulator of Ca2+ and redox signalling in lung fibroblasts, and highlight GPR40, TRPV4, IP3Rs and lysosomal TPCs as potential therapeutic targets for intervening in pulmonary fibrosis." (PMID 42123594, 2026). "A small-molecule TRPV4 inhibitor (GSK2193874) was tested in bleomycin lung fibrosis models and found to reduce lung inflammation and fibrosis by blocking TRPV4–mediated Ca2+ influx in fibroblasts, which is necessary for the TRPV4–PI3Kγ scaffold function." (PMID 40149956, 2025). "Activation of TRPV4 in lung fibroblasts accelerates the differentiation of myofibroblasts and contributes to the progression of pulmonary fibrosis." (PMID 38256251, 2024). "TRPV4 activity has been found to be significantly higher in patients with idiopathic pulmonary fibrosis." (PMID 38256251, 2024). "Like hepatic fibrosis, TRPV4 was upregulated in fibrotic pulmonary tissue and TRPV4-KO mice were protected from pulmonary fibrosis." (PMID 35451372, 2022). "Regarding bleomycin-induced pulmonary fibrosis, the symptoms of fibrosis are weaker in TRPV4-/- mice than in wild type mice, and gene deletion of TRPV4 inhibits myofibroblast differentiation." (PMID 36045746, 2022). "In this review, we describe the role for TRPV4 mechanotransduction in cardiac and lung fibrosis, and we propose TRPV4 as an alternative therapeutic target for fibrosis." (PMID 34831281, 2021).